IRF3 (interferon regulatory factor 3)
Diseases named in the same sentence as IRF3 in open-access papers (continued):
Sharing a sentence is not in itself a finding about the gene and the disease.
infection (continued). "Second, zebrafish TBK1_tv1 and TBK1_tv2 bound to TBK1 and IRF3 in mammalian and fish overexpression systems with/without SVCV infection." (PMID 29441066, 2018). "Since our results show that TBK1 is crucial for hMPV-mediated lfTSLP induction, whereas IRF3 is not, we finally sought to assess if TBK1 regulates the activation of NF-κB during hMPV infection." (PMID 29343779, 2018). "Similar to the infection of MPI cells, and unlike that of BMMs, they exhibited early and strong phosphorylation of p38 and IRF3 and a strong cytokine response." (PMID 28765216, 2017). "Taken together, these results indicate that not only is PKR required for the MDA5-dependent activation of IRF3 and induction of IFNβ expression, but activation of its catalytic function is dependent on MDA5 during VVΔE3L, but not VSV, infection." (PMID 26939124, 2016). "In the absence of PKR, IRF3 nuclear translocation was impaired in response to MDA5 activators, VVΔE3L and encephalomyocarditis virus, but not during infection with a RIG-I-activating virus." (PMID 26939124, 2016). "Additionally, titers of WNVKUN or A30A′ in the serum of infected mice (weanling and adult IRF3−/−/7−/−) and levels of CPE induced in IFNAR−/− MEFs were similar and unpublished data) suggesting that NS1′ protein may not have an essential function in the viral lifecycle in these models of infection." (PMID 25375107, 2014). "Such a model would be consistent with our profiling data, as we observed dramatic RNA changes already at early times (2–4 hours) after infection, whereas TLR3-dependent phosphorylation of IRF3 was not induced until much later (36 hpi)." (PMID 25127040, 2014). "On the other hand, knockdown of IRF3 did not affect the virus production and the expression levels of IFN-α/β remained unchanged after infection of siIRF3-transfected MDCK cells." (PMID 23555825, 2013). "Despite the combined absence of IRF-3, IRF-5, and IRF-7, TKO mice still produced type I IFN after WNV infection, albeit at lower levels in the context of markedly enhanced infection." (PMID 23300459, 2013). "Recognition by innate immune receptors was required for SOCS3 expression, since Socs3 mRNA levels after infection were reduced in the Toll-like receptor adaptor molecule MyD88−/− BMM and BMM incubated with a NF-κB inhibitor but not in Irf3−/− BMM." (PMID 23853585, 2013). "Immunoblot analyses at different time points following infection of cells with these SeV strains confirmed that, unlike SeV WT, SeV H4 activates the RLR pathway as observed by the phosphorylation of both IRF3 and the NF-κB inhibitor IκBα." (PMID 22626058, 2012). "Following infection of fibroblasts with D8, MG132 did not alter the cytoplasmic localization of ICP0 or the ability of cytoplasmic ICP0 to block IRF3 nuclear accumulation or ISG56 induction." (PMID 20454685, 2010). "In agreement with the activation of IRF3, ISG56 induction was detected following infection with SeV or ICP0-null HSV-1 but not with WT HSV-1." (PMID 20454685, 2010). "Despite a higher overall level of IRF3 activation following SeV infection, WT and D8 infection blocked ISG56 production whereas ICP0-null and R7914 infection did not." (PMID 20454685, 2010). "Mice that lack both IRF-3 and IRF-7 were highly vulnerable to lethal infection and cells lacking IRF-3 and IRF-7 had a markedly attenuated IFN-α response." (PMID 19798431, 2009). "A mutant virus containing a single mutation at C protein F170S, which does not affect the P protein sequence, strongly activates IRF-3 and induces IFN-β production, indicating hPIV1 C can circumvent IFN production stimulated by hPIV1 infection." (PMID 21994561, 2009). "We show here that IRF-3 is critical for the induction of IFN-αβ by isolated adenoviral DNA, but not by infection with whole virions in BMDCs." (PMID 19008951, 2008).
infection (continued). "Surprisingly, RIG-I and MDA-5 were not basally expressed in wild-type or IRF-3−/− cortical neurons but were induced in an IRF-3-dependent fashion at 24 and 48 h after infection." (PMID 17676997, 2007). "Both IRF3 and IRF7 were upregulated in lungs, but not nose, with infection." (PMID 40956633, 2025). "While knockdown of IRF3, IRF5, or IRF7 expression had no impact on the efficiency of infection establishment, we observed significant downregulation in IP-10 expression upon IRF5 or IRF3 knockdown and a trend toward significance upon knockdown of IRF7 expression in HIV-infected MDMs." (PMID 40493408, 2025). "PLAAT1 colocalized with IRF3 and IRF7 without or with SVCV infection." (PMID 36172355, 2022). "IRF3 and IRF7 mRNA levels in HRV16 and HRV1B infection were not different from the mock." (PMID 34838080, 2021). "However, infection with WT HSV-1, but not ΔUL46 HSV-1, inhibited the phosphorylation of TBK1 and IRF3 induced by ISD, which is critical for IFN-I production." (PMID 31113902, 2019). "On the other hand, the induction of Gal-9 transcription by HCMV and UV-HCMV which is known to be dependent on both IRF3-mediated type I IFN production and JAK/STAT signaling in this system, was elevated post infection in the primary HFs but not in either of the IFN-abrogated cell lines." (PMID 30871003, 2019). "PMA-differentiated THP-1 cells activate IRF-3 in response to MVA, but not COP or WR, infection." (PMID 29491158, 2018). "While IRF3 normally localized in the cytosol of non-infected cells, we could clearly detect IRF3 into MRV VFs upon either virion or ISVP infection." (PMID 28883463, 2017). "When comparing control shNT-treated with SNRNP200 KD cells in the context of SeV-mediated infection, regardless of whether or not DDX58 or IRF3 was overexpressed, a significant reduction in the IRF3-p386/IRF3 ratios (from 0.6–0.9 to 0.1–0.2) was observed." (PMID 27454487, 2016). "Consistent with data for FluΔNS1, which displayed no dependency on PKR for IFN production, infection of PKR-null MEFs with another RIG-I agonist and strong inducer of IRF3 phosphorylation, Sendai virus (SeV), did not result in a significant defect in IRF3 activation." (PMID 26939124, 2016). "Firstly, when infected onto the plaque assay wells at the same inoculum of 30 pfu per well, PDK53 yielded more plaques when IRF3, STAT1 or NF-kB were silenced, indicating that many PDK53 infections do not normally form visible plaques or foci of infection due to antiviral activation." (PMID 27185466, 2016). "The infection and proliferation of HCVbb in HuS-E/2 cells were enhanced by ectopic expression of a dominant-negative form of IRF-7, but not that of IRF-3, suggesting that IRF-7, rather than IRF-3, plays a primary role in regulation of HCV proliferation in these cells." (PMID 24587086, 2014). "Infected MAVS−/− and IRF3−/−IRF7−/− epithelia show ISG induction in the absence of any detectable IFN upregulation, while IFNAR1−/−IL-28Rα−/− cells, which produce but cannot respond to IFNs, did not express ISGs in response to infection." (PMID 24278020, 2013). "However, we did not detect increased expression or activation of IRF7 or IRF3, respectively, upon A/PR8 infection in wt or pkr−/− AM." (PMID 23468627, 2013). "We have previously shown that NSs inhibits IFN-β expression immediately after infection with the virulent RVFV strain ZH548 (ZH), without inhibiting IFN-β-specific transcription factors such as IRF3, NF-κB and ATF2 that are normally activated and translocated to the nucleus in RVFV-infected cells." (PMID 18225953, 2008). "Interferon regulatory factor 3 (IRF3), but not TANK-binding kinase 1 (TBK1) and IκB kinase epsilon (IKKε), is sequestered into viral inclusion bodies (IBs) upon Ebola virus (EBOV) transcription- and replication-competent virus-like particles (trVLPs) infection." (PMID 38285487, 2024).
infection (continued). "To further examine the interactions of PTK2B with STING, TBK1 and IRF3, we next performed endogenous Co-IP experiments with PTK2B antibody in RAW 264.7 cells with or without HSV1-GFP infection and found that PTK2B only pulled down STING and TBK1 regardless of the HSV1-GFP infection state." (PMID 37989995, 2023). "Immunoblotting assay results showed that PeV-A3 failed to induce STAT1, STAT2, IRF3, and NFκB p65 activation in FBS medium-maintained GBM cells; in contrast, phosphorylation of STAT1, STAT2, IRF3, and total NFκB p65 were detected in hPL-medium-maintained GBM cells with PeV-A3 infection." (PMID 35891479, 2022). "Infection at an MOI of 1 resulted in few to no infected cells at 6 hpi; however, at an MOI of 10, where most of the cells were infected, we observed a reduced level of phosphorylated IRF3 in PR1NS53UTR compared with PR1, indicating early inhibition of the type I IFN response." (PMID 32366663, 2020). "The absence of IRF-3 activation upon COP or WR infection could be explained by (i) an ability of these viruses to mask their dsDNA genome in a manner that is lost in MVA, or (ii) the production of viral factors that prevent IRF-3 activation." (PMID 29491158, 2018). "Kinetics of virus replication, transcription factor (c-Jun, p50 and IRF-3) activation and immune response gene (IL-6, IL-1beta, IFN-alpha and Mx) expression were studied at four different time points (6, 12, 24 and 48 hours) post infection and compared to non-infected controls." (PMID 24252391, 2013). "Based on this, we suggest that the VZV-mediated phosphorylation of IRF3, which leads to its up-shift in SDS-PAGE, does not correspond to the activated hyperphosphorylated forms III and IV that are observed, for example, during an infection with the Sendai Virus." (PMID 21347389, 2011). "However, vv811 did not reduce IRF-3 activation as effectively as COP, but rather to the levels induced by vv811 infection in the absence of DNA stimulation, suggesting that this baseline activation on infection may be induced by a response that is unrelated to DNA sensing." (PMID 29491158, 2018).
tumor (268 papers, 2009 to 2026). "Consistently, tumor tissue staining revealed that p‐IRF3 was significantly upregulated in tumor‐associated macrophages in tumors treated with Nb289‐MG1655‐CR‐mediated PTT, indicating the activation of the STING pathway in macrophages." (PMID 38888519, 2024). "Positive associations of several TF-encoding genes such as ZNF683 (HOBIT), STAT2, and IRF3 with the abundances of tumour-infiltrating CD56bright NK and CD8+ TEM cells were observed." (PMID 39877370, 2024). "Briefly, STING agonists repolarize tumor‐associated macrophages from the M2 type towards the M1 type through NF‐κβ/IRF3 activation and type I IFN upregulation." (PMID 37560754, 2023). "cGAMP activates the downstream STING–IRF3 signaling pathway, and phosphorylated IRF3 accumulates slowly in cells, relieving the inhibitory effect of Bcl-xL on mitochondrial outer membrane permeability and causing tumor cell apoptosis." (PMID 35536585, 2022). "TBK1 and IRF3 polymorphisms were investigated for their effects on tumor growth and vascularization and thus on response to bevacizumab therapy." (PMID 36432658, 2022). "Intratumoral administration of TTI-10001 in murine models of syngeneic tumors was found to be safe and associated with increased levels of phospho-IRF3, pro-inflammatory cytokines, and anti-tumor activity." (PMID 34070756, 2021). "Consistently, related research observed host anti-tumor CD8+ T cells responses loss when STING or IRF3 gene was knocked out in various tumor models." (PMID 34956229, 2021). "Previous in vitro studies on tumor cells also indicated an oncogenic potential upon knock-out or mutation of IRF3, while overexpression decreased cell growth and cell cycle progression, partly through blocking DNA synthesis and apoptosis induction." (PMID 32545331, 2020). "High levels of IRF3 were observed in tumor-associated macrophages with immunoregulatory properties and type 1 IFN can be a substantial anti-inflammatory mediator in certain contexts." (PMID 32312307, 2020). "These consistent observations suggest that Wnt/β-catenin underlies the IRF3-mediated suppression of tumor cell growth." (PMID 33188184, 2020). "We found that the absence of type I IFN mRNA after DMXAA injection in Spont-PyMT mice was associated with a dramatic defect in IRF3 phosphorylation in the tumor ecosystem, both in tumor cells and in immune-infiltrating cells." (PMID 31511510, 2019). "Both IFNβ and IP-10 are determined as IRF-3-dependent genes and alterations in their expression levels have been associated with inflammatory diseases, immune dysfunction, and tumor development." (PMID 23658645, 2013). "IRF3 expression appears linked to histological subtypes, supporting its role in tumor biology." (PMID 41706744, 2026). "Interestingly, we noted that low IMMT was associated with a suppressed immune response to tumor cells and interferon regulatory factor 3 (IRF3)-mediated induction of type I interferons." (PMID 37240154, 2023). "STING-deficient mice and IRF3-deficient mice exhibited defective tumor rejection." (PMID 32174922, 2020). "Next, we detected numerous lymphocyte development and function associated pathways that are significantly associated with ZNF683 (HOBIT), STAT2, and IRF3 expression, indicating that these TFs may regulate the priming, and their downstream functionalities of tumour-infiltrating NK and CD8+ T cells." (PMID 39877370, 2024). "Finally, our results show that tumor tissues in GBM patients highly express IRF3 and IRF7, encoding interferon regulatory factors that can lead to the transcription of caspase-11, which is important for noncanonical NLRP3 inflammasome activation, via activation of the JAK/STAT pathway." (PMID 31133717, 2019). "PTEN, a well-known tumor suppressor, not only plays a crucial role in tumorigenesis but also enhances antiviral immunity by regulating IRF3 phosphorylation and promoting type I interferon production." (PMID 42227768, 2026).
tumor (continued). "Histological staining further revealed that administration of YJ1206 significantly elevated the levels of p-STING and p-IRF3 in tumor samples, demonstrating that YJ1206 treatment induced STING activation in vivo." (PMID 40955658, 2025). "This downregulation of SURF4 enables STING protein retention at the Golgi apparatus, subsequently activating the downstream p-IRF3 axis and interferon signaling, ultimately enhancing T cell-mediated anti-tumor immunity." (PMID 40846839, 2025). "For example, BART encoded EBV circRNA, circBART2.2, binds RIG-1 and activates the transcription factors interferon regulatory factor 3 (IRF3) and NF-κB, exacerbating the inflammatory immune response to promote tumor escape." (PMID 40733622, 2025). "This recognition triggers a cascade of phosphorylation events involving STING, TBK1, and IRF3, ultimately leading to the secretion of type I interferons, which induce an anti-tumor immune response." (PMID 40761260, 2025). "In RTT IRF3/7 tumours, despite high levels of PGE2, the increased levels of IFN-I cytokines mediated inflammatory monocyte formation." (PMID 39604727, 2025). "The results demonstrated a significant increase in the expression levels of γ-H2AX, p-STING, and p-IRF3 in the tumor tissues of mice treated with CuB." (PMID 40896699, 2025). "Intratumoral injection of cGAMP20,21, or systemic administration of metabolically stable synthetic STING agonists, has been shown to inhibit tumor growth in a variety of syngeneic mouse tumor models by promoting STING/IRF3 signaling." (PMID 40216780, 2025). "In parallel, STING-mediated activation of interferon regulatory factor 3 (IRF3) can induce PD-L1 upregulation in tumor cells as a compensatory resistance mechanism." (PMID 40697412, 2025). "In RTT IRF3/7 tumours, inflammatory monocytes were the predominant population, together with a TAM cluster with enhanced stimulatory functions (TAM H2-Ab1) that was absent in RTT tumours." (PMID 39604727, 2025). "An overall increase was observed for the total expression of p‐IRF3 in the tumour mass and for its specific expression in F4/80+ TAMs after treatment." (PMID 40240911, 2025). "We found that elevating T cell NAD+ levels activates the STING axis and downstream p-IRF3 signaling, thereby enhancing T cell anti-tumor function." (PMID 40846839, 2025). "We performed scRNA-seq and flow cytometry analyses of CD45+ cells from YUMM1.7OVA NTT tumours, RTT control (CTRL) tumours, RTTPtgs1/2 KO tumours and RTT IRF3/7 overexpressing tumours 72 h after ACT." (PMID 39604727, 2025). "There are potential interactions between IRF3 and components of the NF-κB signaling pathway, which provide an inflammatory tumor microenvironment promoting tumor survival and metastasis." (PMID 39706834, 2024). "Alterations in the expression of DDX58, MAVS, C6orf150, TMEM173, IKBKE, TBK1 and IRF3 were analyzed across different tumor samples using cBioPortal." (PMID 38817870, 2024). "Since most of the IRF3 has already been converted to P‐IRF3 in JAWSII cells, anti‐IRF3 detected only a limited IRF3 amount, whereas the opposite was observed for both tumor cell lines (Pan02 and SCCVII)." (PMID 38400597, 2024). "The protein expression level of TBK1 also exhibited an upward trend in the tumor metastasis group, whereas the expression level of IRF3 demonstrated an opposing phenomenon." (PMID 38817870, 2024). "Meanwhile, the phosphorylation of STING, TBK1, and IRF3 activity were both abolished when using mtDNA-depletion versus control tumor mouse CRC cells." (PMID 38853246, 2024). "Then, the signal cascades and finishes in interferon regulatory factor 3 (IRF3) and NF-κB targets in the nucleus, leading to the secretion of type-I interferon, which is vital to tumor-specific T cells." (PMID 39273044, 2024). "Initially, we examined the expression levels of key genes within the innate immune pathway, namely DDX58, MAVS, C6orf150, TMEM173, IKBKE, TBK1 and IRF3, across diverse tumor and non-tumor tissues." (PMID 38817870, 2024).